LEP (leptin)
Diseases named in the same sentence as LEP in open-access papers (continued):
Sharing a sentence is not in itself a finding about the gene and the disease.
Obesity (continued). "Conversely, another possible explanation could be that poor SQ can be linked to increasing risk for obesity via hormonal regulations, such as leptin." (PMID 35270837, 2022). "Obesity determined through the body mass index has a significant correlation with higher values of leptin and an increased risk of CRC and death, whereas improved survival in the case of moderate adiposity may indicate a protective state for CRC." (PMID 35563103, 2022). "Since brain Rap1 activation has emerged as a causative factor for decreases in leptin responsiveness and obesity, the reduced activity of brain Rap1 signaling may coordinately contribute to the phenotypes of the oral YHIEPV treatment." (PMID 35597815, 2022). "Increased white adipose tissue in overweight and obesity, and increased levels of fat-specific cytokines, above all leptin, have been associated with proliferative signaling, inflammation, angiogenesis, that can sustain BC growth, tissue invasion, and metastasis." (PMID 35276833, 2022). "The AG/AA polymorphisms in the leptin and adiponectin genes alter the serum levels of these adipokines and predispose them to obesity, and many anthropometric, biochemical, and hormonal markers are altered, demonstrating early consequences for the health of these obese children and adolescents." (PMID 35703718, 2022). "Elevated levels of leptin in obesity are linked to hypertension and acute cardiovascular events." (PMID 35890325, 2022). "The use of drugs or specific bioactive food components with anti-inflammatory properties to reduce the inflammatory state associated with obesity, especially in the hypothalamus, may help to overcome leptin resistance." (PMID 36364892, 2022). "PTP1B deficient mice are allergic to leptin and resistant to diet-induced obesity." (PMID 36615730, 2022). "Hormones, especially leptin, insulin, and adrenal hormones, have been associated with satiety, glucose homeostasis, and adipogenesis, while hypothyroidism impairs energy metabolism, favoring obesity." (PMID 35631188, 2022). "PAI-1 deficiency and PAI-1 inhibitor treatment can protect against HFD-induced obesity, insulin resistance, and liver steatosis, partially via the enhanced energy expenditure associated with alleviated hypothalamic leptin resistance and increased adipocyte lipolysis." (PMID 35909571, 2022). "The association between obesity and cancers may also be partially supported by the high leptin level in blood circulation; leptin’s involvement in the pathogenesis of various cancers, including CRC, has already been reported." (PMID 35563103, 2022). "Based on the high frequency of the A allele, obesity in Latin America could be predisposed by SNPs in the LEP gene." (PMID 36532520, 2022). "On the other hand, the leptin serum level and LEP mutations are causal for obesity, being highly correlated with body fat mass and sequence variations in the leptin coding gene, which may affect the expression of leptin." (PMID 35563103, 2022). "Indeed, as an increase in circulating leptin and a decrease in adiponectin levels are observed in obesity, a low plasma A/L ratio is associated with a worsened AT secretory dysfunction." (PMID 35436409, 2022). "Hence, only a relatively small number of LEP polymorphisms have so far been associated with obesity." (PMID 35563103, 2022). "Recently, a relatively new hypothesis states that the suppression of immune surveillance caused by sleep deprivation at night, obesity induced by leptin secretion disorder, and changes in intestinal microbiota are also associated with the increased risk of BC." (PMID 35702390, 2022). "Our results suggest that leptin may partly explain part of the reported association between obesity and kidney disease." (PMID 35619087, 2022).
Obesity (continued). "Although leptin therapy has been shown to reverse metabolic and neuroendocrine dysfunctions in obese individuals with congenital leptin deficiency, most cases of common obesity are associated with resistance to elevated levels of endogenous leptin, and to exogenously delivered leptin as well." (PMID 35527735, 2022). "The reduction in adipose tissue after the surgical treatment of obesity causes a reduction in leptin levels and an increase in adiponectin levels, and these changes may lead to an increase in bone resorption." (PMID 36382751, 2022). "However, additional rare LEP mutations were reported in humans to be associated with obesity and its related comorbidities." (PMID 35563103, 2022). "Thus, PTP1B has been linked to central leptin resistance in humans and in a variety of animal models of obesity and aging." (PMID 35563589, 2022). "Our findings could be explained by the hypothesis that obesity itself can play a role in autoimmunity, in particular through the action of leptin, and that high normal values of TSH may be linked to pro-inflammatory status and autoimmune activation." (PMID 36079055, 2022). "Compared to lean controls, mRNA levels of GPSM1 in both epididymal WAT (eWAT) and subcutaneous WAT (scWAT) were significantly higher in mice with high-fat diet (HFD)-induced obesity (DIO) or genetic obesity caused by leptin (Ob/Ob) or leptin receptor (Db/Db) deficiency." (PMID 36434066, 2022). "Furthermore, elevated levels of leptin associated with obesity can inhibit LH-stimulated estradiol production in granulosa cells, as well as inhibit the insulin-induced ovarian steroidogenesis, thus impeding follicle development." (PMID 36139133, 2022). "Additionally, the link between tooth brushing and obesity is thought to be due to leptin-linked pathways that controls the balance between energy and appetite." (PMID 35902918, 2022). "Our findings demonstrate that these SNPs have sex-specific associations with BMI in IVDD patients, and that obesity and sex, particularly among obese women, may modify the LEP transcription effect." (PMID 36293132, 2022). "Low leptin is related to malnutrition and an increased risk of infection, while high leptin correlates with obesity, leptin resistance, low-grade inflammation, neurodegenerative and autoimmune diseases, an M1 macrophage phenotype, decreased lymphocytes, and a severe course of COVID-19." (PMID 35406000, 2022). "Resistance to Leptin is considered one of the main causes of obesity." (PMID 36245943, 2022). "Obesity is generally associated with leptin resistance, and if DRNVglut3 neurons are functionally downstream, it would suggest that modulating their activity could reduce the weight of leptin-resistant obese animals." (PMID 36411386, 2022). "Leptin mutations cause hyperphagia, which results in obesity." (PMID 35563777, 2022). "Laboratory studies revealed that short sleep could increase ghrelin level and decrease leptin level in the body, which may alter eating habits and eventually predispose overweight/obesity in the future." (PMID 36045412, 2022). "Serum Fetuin B was positively associated with leptin in obesity." (PMID 35896788, 2022). "Previous studies reported that mutations in the leptin gene cause severe obesity and may also contribute to the complications associated with obesity." (PMID 36619235, 2022). "Additionally, hormonal mechanisms underlying the anti-obesity effect of chitoglucan were elucidated through the analysis of serum levels of leptin and resistin." (PMID 36612600, 2022). "This review aims to summarize the current knowledge on the potential associations of leptin genetics with the main pathogenic pathways of obesity and CRC, in an attempt to understand the molecular mechanisms of these associations, in the context of inconsistent and contradictory data." (PMID 35563103, 2022). "Furthermore, an obesity-induced increase in leptin, insulin, and proinflammatory cytokine levels can cause hypogonadism." (PMID 36431285, 2022).
Obesity (continued). "It is unclear whether leptin resistance or other aspects of obesity make individuals with OSA more susceptible to IH-induced cardiac remodeling, warranting further investigation." (PMID 36160851, 2022). "Mutations in the LEP gene have been significantly associated with obesity." (PMID 36532520, 2022). "Specifically, Mt remodeling in hypertensive and insulin-resistant lean models (Ren2 rat models), lean mice with streptozotocin-induced diabetes, obesity models including diet-induced obesity, genetic leptin-deficient ob/ob, and leptin receptor-deficient db/db diabetic mice are examined." (PMID 35563211, 2022). "Farooqi (2005) reported that inherited human leptin deficiency in patients caused severe early-onset obesity (e.g., 8 years and 86 kg, or 2 years and 29 kg) due to a frame-shift mutation in the homozygous obesity leptin gene (deletion of G133) and a truncated protein." (PMID 36232301, 2022). "Furthermore, a meta-analysis demonstrated a positive association between leptin levels and the incidence of breast cancer, with the strongest evidence seen in postmenopausal women with overweight/obesity." (PMID 36401194, 2022). "In addition, the knock-out of the Klotho gene in leptin-deficient mice reduces obesity and increases insulin sensitivity." (PMID 35053218, 2022). "Furthermore, TLR4, associated with obesity-related inflammatory responses, is activated by leptin through the JAK2–STAT3-CD14 signaling pathway to promote OA." (PMID 35270000, 2022). "In humans, mutations of the LEP gene have been associated with obesity in different populations." (PMID 35978633, 2022). "An SNP (rs7799039) in the LEP gene has been associated with obesity." (PMID 36532520, 2022). "Treadmill training was used in leptin-deficient obesity mice (n = 1)." (PMID 35742478, 2022). "Leptin is a hormone encoded by the obesity gene (LPER) on human chromosome 7." (PMID 36522620, 2022). "The effect of cocoa-based product intake on body fat and obesity could be explained by an associated reduction in plasma adipokine (leptin and adiponectin) concentrations, although the mechanisms involved still need to be clarified." (PMID 35873437, 2022). "Therefore, bodyweight reduction through a hypocaloric diet decreases visceral adipose tissue, Leptin, IL-6 and IL-1a while increasing ketone bodies, attenuating inflammatory response linked to psoriasis and obesity." (PMID 35886846, 2022). "Moreover, CRTC1 seems necessary to protect against hepatic steatosis, which is strongly associated with obesity and metabolic syndrome, and to modulate leptin’s glucoregulatory actions in insulin-dependent diabetes." (PMID 35242012, 2022). "Cesarean delivery was associated with a lower umbilical leptin concentration and it reduces the rate of early breastfeeding both of which were reported to be associated with an increased risk of later overweight and obesity." (PMID 36159318, 2022). "The unfavorable status of vitamin D in patients with obesity may also be related to 1.25 dihydroxyvitamin D deficit in association with high leptin levels." (PMID 35887780, 2022). "Indeed, leptin is an adipocyte-derived hormone encoded by the obesity (ob) gene that regulates many physiological processes including energy homeostasis, appetite and immune function." (PMID 36313760, 2022). "The altered levels of leptin in animal models of obesity may reflect the mechanism underlying obesity." (PMID 35529938, 2022). "Therefore, we compared the effects of TZDs including PGZ and rosiglitazone (RGZ) in ob/ob mice and Lepmkyo/Lepmkyo rats, models of leptin-deficient obesity, and A-ZIP/F-1 mice and seipin knockout (SKO) rats, models of generalized lipodystrophy." (PMID 35013417, 2022). "A previous study has shown that simple obesity is associated with leptin resistance." (PMID 35529938, 2022).
Obesity (continued). "Given that in Neotomodon the obesity condition occurs spontaneously only in a subset of the captive mice, may be cause of some genetic deficit related to leptin signaling or leptin resistance that in this species still needs to be identified." (PMID 35990356, 2022). "Therefore, impairments in the central signaling pathways of insulin and leptin are associated with energy imbalance and obesity development." (PMID 35445066, 2022). "However, future investigations using in vivo models are necessary to confirm the role of leptin in inducing lung epithelial cell phenotypic switching in obesity-associated asthma." (PMID 35888038, 2022). "However, many GDM patients are associated with obesity, and the levels of adipokines such as leptin and adiponectin in their bodies are very different from those of normal pregnant women." (PMID 36615730, 2022). "Patients with severe obesity may have transient hypothyroidism caused by an increase in leptin-levels that resolves following Roux-en-Y gastric bypass (RYGB)." (PMID 34992244, 2022). "In addition to the influence of proinflammatory cytokines such as IL-6 or TNF-alpha, growth-stimulating effects of various obesity-associated hormones such as leptin, estrogen, or insulin have been well described." (PMID 36231132, 2022). "Therefore, only a few studies have analyzed the possible associations among leptin, lymphoma, and obesity." (PMID 36555171, 2022). "Leptin antagonizes insulin, thereby causing the breakdown of insulin receptors, lowering insulin sensitivity, and elevating glucose synthesis, which subsequently leads to the development of obesity and diabetes mellitus." (PMID 36232660, 2022). "Continued analysis of leptin mutations along phenotypic and clinical data may improve our understanding of monogenic obesity." (PMID 36121795, 2022). "Impaired leptin signaling is associated with brain structural remodeling changes in obesity and diabetes and thus may play a role in AD [Hayden and Banks, 2021)]." (PMID 36389068, 2022). "Moreover, and possibly in connection with the key role of SOCS3 and PTP1B in leptin action, endoplasmic reticulum (ER) stress has also been identified as a mechanism implicated in the development of obesity-associated leptin resistance." (PMID 34523036, 2022). "A role for visceral adipose tissue (VAT) in the myeloid bias in obesity was suggested from studies where VAT from leptin-deficient Ob/Ob mice was transplanted into wild-type recipients and recapitulated the obesity-associated myelopoiesis, neutrophilia and monocytosis." (PMID 35216355, 2022). "Furthermore, elevated levels of leptin are overexpressed at a gene level in adipose tissue and are associated with leptin resistance, which is implicated in obesity, inflammation, and breast tumourigenesis." (PMID 36451148, 2022). "In addition to this, obesity leads to high levels of leptin, which acts as a cause for the release of pro-inflammatory cytokines and an exaggerated release of insulin leading to insulin resistance." (PMID 36355134, 2022). "Leptin is used in therapies for leptin-deficient patients and is a possible biomarker for obesity management therapies, since leptin resistance is related to obesity and leptin levels vary with dieting regimens." (PMID 35884340, 2022). "In some cases, risk factors like obesity, may also lead to tumorigenesis, mediated by increased leptin and decreased adiponectin." (PMID 36618350, 2022). "For instance, obesity increases the risk of hypertension, diabetes, stroke and leptin dysregulation that may affect, per se, cognitive performance." (PMID 35741662, 2022). "Vitamin C, vitamin E, and β-carotene deficiencies may alter the genetic expression of leptin important in regulating food intake energy expenditure and constancy of adipose tissue thus leading to leptin resistance and increased adiposity and obesity risk." (PMID 35081959, 2022).
Obesity (continued). "We may only speculate that time of exposure to obesity, different expressions of TIMPs, and differences in leptin cellular signaling may be considered cause for such inconsistency." (PMID 35457013, 2022). "Dysregulation of leptin or its receptor (LEPR) causes severe obesity and diabetes." (PMID 36189793, 2022). "Therefore, PsO patients subjected to high-fat diets have a higher risk of obesity and to display higher levels of leptin." (PMID 36297008, 2022). "Indeed, hepatocyte hypertrophy/steatosis and hepatomegaly are also observed in genetic (e.g., leptin (ob/ob) or leptin receptor (db/db) deficient mice) and diet-induced mouse models of obesity and IR." (PMID 35409319, 2022). "Furthermore, obesity as a result of greater energy intake is associated with an elevated level of leptin." (PMID 35883173, 2022). "Leptin, a 16 kDa protein secreted by adipocyte and the key cytokine linked with obesity and T2DM, acts as an anorectic hormone that restricts lipid storage and body weight gain, inhibits ectopic lipid accumulation, attenuates lipotoxicity, and improves insulin sensitivity." (PMID 36046814, 2022). "Lack of leptin signaling inrats and humans causes obesity and infertility." (PMID 36273315, 2022). "Moreover, the loss of leptin can lead to problems such as overeating, decreased energy expenditure, and severe obesity, which are important risk factors affecting glucose homeostasis." (PMID 35784545, 2022). "Currently, leptin, resistin, and visfatin are the most widely used pro-inflammatory adipokines in experimental studies, as well as in clinical trials of anti-diabetic preparations and other therapeutics targeting obesity-associated diseases." (PMID 36499312, 2022). "Obesity is linked to an elevated content of leptin in the expanding adipose tissue, and hyperleptinemia could result into low-grade systemic inflammation in obesity, illustrating a possible function of leptin in obesity-triggered inflammation." (PMID 35273574, 2022). "This unfavorable leptin/adiponectin ratio has been proposed as a functional biomarker of adipose tissue inflammation and seems to be a good indicator of cardiometabolic risk associated with obesity and metabolic syndrome." (PMID 35057485, 2022). "However, obesity conditions with leptin deficiency or leptin receptor deficiency suppressed endometriosis development." (PMID 36140261, 2022). "In addition, mice leptin-deficient ob/ob or leptin receptor (LepRb)-null db/db mice present hyperphagia, obesity, and alterations in the gut microbiota." (PMID 36153588, 2022). "Obesity, increased leptin, and leptin resistance are associated with severe COVID-19." (PMID 35666734, 2022). "For some variants in LEP, heterozygous carriers suffering from obesity have been reported." (PMID 36121795, 2022). "Under physiological conditions, adipocytes in perivascular adipose tissue help to regulate vascular tone by releasing vasoactive molecules, including leptin, and these vasodilatory mechanisms may be impaired due to leptin-resistance associated with obesity." (PMID 35783833, 2022). "In the present study, we hypothesize that there is an association between reduced z-scores of circulating leptin levels and diagnosis of steatosis hepatis in pre-pubertal children with obesity." (PMID 35677722, 2022). "Associations between micronutrient deficiencies and obesity have been reported in various populations, and such deficiencies may affect leptin and insulin metabolisms." (PMID 35498399, 2022). "Previous studies have shown that obesity-associated cancers are associated with overproduction of hormones (estrogen, leptin, and insulin-like growth factor), induction of reactive oxygen species (ROS) production by free fatty acids, and changes in the gut microbiome." (PMID 36611881, 2022).